KRTAP11-1 (keratin associated protein 11-1)
Description:
In the hair cortex, hair keratin intermediate filaments are embedded in an interfilamentous matrix, consisting of hair keratin-associated proteins (KRTAP), which are essential for the formation of a rigid and resistant hair shaft through their extensive disulfide bond cross-linking with abundant cysteine residues of hair keratins. The matrix proteins include the high-sulfur and high-glycine-tyrosine keratins.
Synonyms: KAP11.1; HACL-1
Tractability: No criterion of Open Targets' tractability assessment is met for any kind of drug.
Gene: Protein-coding gene on chromosome 21 (30,880,644 to 30,881,580, reverse strand). Ensembl gene ENSG00000182591.
Pathways (Reactome):
Developmental Biology: Keratinization
Gene Ontology:
Molecular function: protein binding; structural molecule activity
Cellular component: cytosol; keratin filament
Genetic constraint (gnomAD): Loss-of-function variants: 17 observed, 14.46 expected, observed/expected ratio (o/e) 1.18, 90% interval 0.8 to 1.73. The upper end of that interval is the gene's LOEUF score, 1.73, which puts it in group 6 of 6, group 1 being the genes least tolerant of losing a copy. Missense variants: 181 observed, 211.6 expected, observed/expected ratio (o/e) 0.86, 90% interval 0.76 to 0.97. Synonymous variants: 69 observed, 86.71 expected, observed/expected ratio (o/e) 0.8, 90% interval 0.65 to 0.97.
Homologues: Orthologues: chimpanzee KRTAP11-1 (98% identical), macaque KRTAP11-1 (89% identical), mouse Krtap11-1 (82% identical), rat Krtap11-1 (82% identical), rabbit KRTAP11-1 (82% identical), pig KRTAP11-1 (80% identical), guinea pig KRTAP11-1 (79% identical), dog KRTAP11-1 (77% identical). Paralogues in human: KRTAP13-1 (40% identical), KRTAP13-2 (37% identical), KRTAP26-1 (34% identical), KRTAP13-3 (32% identical), KRTAP13-4 (32% identical), KRTAP27-1 (29% identical), KRTAP15-1 (26% identical), KRTAP25-1 (15% identical).
Diseases named in the same sentence as KRTAP11-1 in open-access papers:
KRTAP11-1 is named in the same sentence as 1 disease in open-access papers, as found by Europe PMC text mining. Sharing a sentence is not in itself a finding about the gene and the disease. The quoted sentences say what the papers report.
Salmonella Infections (1 paper, 2011). Infections with bacteria of the genus SALMONELLA. "Other top-ranked differentially expressed genes in the LS1 pigs such as KRTAP11-1, TAF1B and BTBD10, have not been associated with Salmonella infection previously." (PMID 22174891, 2011).